GLS (glutaminase)
Diseases named in the same sentence as GLS in open-access papers (continued):
Sharing a sentence is not in itself a finding about the gene and the disease.
cancer (continued). "Of the three known mammalian glutaminase isoforms, the expression of the GAC splice-variant (encoded by the GLS1 gene) is modulated by MYC, GAC is also increased in some cancers and seems to be critical for the malignant cell’s transformation and survival." (PMID 29156762, 2017). "Based on these findings, we hypothesize that the use of metformin for OPMD patients could target glutaminase, potentially reducing the risk of progression to cancer." (PMID 39767805, 2024). "Due to the increased susceptibility of mIDH cancer cells to oxidative stress, the effect of mIDH inhibitors could be enhanced by combining them with a GLS inhibitor." (PMID 39063158, 2024). "Drugs that target intrinsic metabolic vulnerabilities (e.g., GLUT1 inhibitors, PDK4 inhibitors, or glutaminase inhibitors) predispose cancer cells to death, which is triggered by decreased nicotinamide adenine dinucleotide phosphate generation or increased reactive oxygen species accumulation." (PMID 37842240, 2023). "Similarly, the lncRNA CCAT2 (Colon cancer-associated transcript 2) directly binds to intron 14 of glutaminase (GLS) pre-mRNA and enhances the recruitment of the cleavage factor I (CFIm) complex." (PMID 35427215, 2022). "High expression of GLS1 (GLS) is associated with poor prognosis in human cancers." (PMID 36381236, 2022). "In drug sensitivity analysis and immune checkpoint analysis, the results showed that CDKN2A, DLAT, PDHA1 and GLS were negatively associated with some or most drugs in the cancer therapeutic response portal database, and the expression of DLST was positively correlated." (PMID 36588699, 2022). "Thus, except for ASNS-deficient cancer cells, ASNase’s glutaminase activity should be considered in the clinic." (PMID 35857457, 2022). "Telaglenastat (CB-839) is an investigational, first-in-class, selective, orally bioavailable, small molecule inhibitor of both splice variants (KGA and GAC) of glutaminase, currently under clinical investigation for the treatment of several cancers including RCC." (PMID 34731180, 2021). "The main enzymes associated with cancer and anticancer include asparaginase, acyltransferase, α-glucosidase, α-amylase, β-glucosidase, β-glucuronidase, gelatinase, glutaminase, laccase, lactate dehydrogenase, triacylglycerol lipase, mono phenol mono-oxygenase, and xylan endo 1,3, β-xylosindase." (PMID 34070936, 2021). "Consequently, the cancer-associated fibroblasts reportedly increased aspartate synthesis through upregulated GLS." (PMID 33718214, 2021). "In this context, the authors proposed that the use of glutaminase inhibitors alone or in combination with NRF2 inducers might be a valid therapeutic strategy to target different cancers respectively carrying functional or mutated forms of the KEAP1 gene." (PMID 32443774, 2020). "While overwhelming evidence points to GLS isozymes as oncogenic proteins, underlying metabolic reprogramming leading to cancer growth and proliferation in Gln-addicted tumors, the role of GLS2 isozymes in tumor biology has not yet been elucidated and needs further clarification." (PMID 32042057, 2020). "The addiction of LUAD tumors harboring Nf1 mutations to glutamine made them susceptible to glutaminase and Psat1 inhibitors, a strategy that could potentially apply to additional cancers with alterations in the NF1–FAK1 pathway." (PMID 31036704, 2019). "KEAP1 mutations predict sensitivity to glutaminase inhibitors across multiple cancer subtypes." (PMID 28967864, 2017). "The increased levels of both ROS and GLS activity after ENO1 silencing prompted us to investigate whether ENO1-deficient cancer cells could be sensitized to the inhibition of anabolic glutamine metabolism." (PMID 26734996, 2016). "Importantly, this not only leads to elevated mitochondrial glutaminase activity, but also causes cancer cells to become more dependent on glutamine-mediated anaplerosis." (PMID 27089238, 2016).
cancer (continued). "Thus, expression of human GLS gene has been associated to oncogene c-Myc through a miRNA mechanism allowing overexpression of K-type GA proteins in parallel with cancer cell proliferation." (PMID 22679499, 2012). "A differential function of GA proteins was first suggested by our group after examination of their pattern of expression in several cancer cell lines and human tumors: GLS isoforms were associated to tumorigenesis while GLS2 were ascribed to cell differentiation." (PMID 22679499, 2012). "Moreover, several studies have reported that targeting glutaminase is of particular interest in cancer treatment, as increased glutaminolysis has been associated with metastatic cells, and glutamate produced from glutamine is associated with cell invasion and migration." (PMID 40943167, 2025). "In addition, there are several other genetic alterations associated with the glutamine dependency of cancer, and these mutations in genes may influence the extent to which tumor cells rely on glutaminase metabolism." (PMID 38459595, 2024). "In addition, LKB1 and KEAP1/NRF2 pathways synergistically promote metabolic reprogramming toward enhanced glutamine dependence in lung adenocarcinoma with mutated KRAS, and they also enhance the sensitivity of cancer cells to CB-839 (GLS inhibitor) in vitro and in vivo." (PMID 36959802, 2023). "Similarly, targeting glutamine metabolism through GLS inhibition could provoke the lethality of ASS1-deficient cancers and is currently being evaluated in GIST and NF1-mutated cancers." (PMID 34294128, 2021). "Having established that UPS and glutamine-sensitive STS subtypes express higher GLS levels, we determined whether a small molecule GLS inhibitor, Telaglenastat (CB-839), currently in clinical trials for multiple cancer types, is effective in causing UPS and STS cell death." (PMID 31980651, 2020). "Indeed, GLS is directly linked to redox balance in cancer cells." (PMID 31429768, 2019). "Upregulation of SLC25A6 expression induced by the glutaminase inhibitor CB-839 sensitized cancer cells to the Bcl-2 inhibitor ABT-199." (PMID 42020360, 2026). "Glutaminase (GLS) is commonly overexpressed in numerous malignant tumors and acts as an oncogene to support cell growth and tumor progression, making it a target for cancer treatment." (PMID 41727907, 2026). "The "glutamine addiction" of cancer cells has made glutaminase an attractive anticancer drug target." (PMID 41847292, 2026). "Compound 968 is a glutaminase inhibitor that is widely used to probe cancer cells' dependence on glutaminase activity." (PMID 41847292, 2026). "Although several studies have explored the metabolic roles of GLS in cancer progression and therapy, the precise mechanisms through which GLS modulates radiosensitivity in LUAD remains poorly understood." (PMID 40308578, 2025). "An elevated GLS activity can therefore provide nutritional benefits for rapidly reproducing cells, such as cancer." (PMID 39859271, 2025). "Inhibition of glutaminase activity has emerged as a promising strategy for cancer therapy, particularly in tumors reliant on glutamine metabolism." (PMID 40850948, 2025). "The upregulation of GLS in CRC tissues reflects its important role in maintaining the metabolic flexibility of cancer cells, supporting their growth and survival." (PMID 41154605, 2025). "Our findings support further evaluation of glutaminase inhibition, particularly CB-839, as a means to restore antitumor immunity in MTAP-deficient cancers and to enhance the efficacy of immune checkpoint blockade in tumors that are otherwise resistant." (PMID 41246302, 2025). "We highlight the synergy between glutaminase inhibitors and PD-1 blockade in reinvigorating CD8+ T cell function, and the role of lipid-loaded cancer-associated fibroblasts in shielding tumors from ferroptosis." (PMID 40253354, 2025).
cancer (continued). "Metformin serves as a beneficial component when used with glutaminase inhibitors (CB-839) and lactate dehydrogenase inhibitors to target the metabolic differences of cancer cells." (PMID 40805165, 2025). "Inhibitors of glutaminase, such as CB-839 (telaglenastat), have shown potential in preclinical models by selectively targeting glutamine-addicted cancer cells." (PMID 39997327, 2025). "The results demonstrated that the GLS gene exhibited elevated levels of expression in cancer cells and immune cells (including T cells, B cells, and dendritic cells), while the PDHA1 gene demonstrated comparatively reduced levels of expression in tumor cells." (PMID 41050056, 2025). "Conversely, glutaminase (GLS), primarily localized in the mitochondria, catalyzes the conversion of glutamine to glutamate—a reaction essential for the rapid proliferation of cancer cells— and was found to be decreased." (PMID 40429796, 2025). "Although glutamine is essential for organisms and there is evidence that supports the beneficial role of glutamine in cancer state and cardiometabolic disorders, dysregulation of glutaminase and glutamine synthetase promotes the anabolic adaptation of tumors." (PMID 40725116, 2025). "As, glutaminase functions to hydrolyze glutamine, it creates scarcity of glutamine to cancer cells thereby building up oxidative stress and further leading to cancer cell death." (PMID 40121594, 2025). "This draws attention to the potential utilization of GLS inhibitors in combination therapy as a novel approach to treating glutamine-dependent cancers because of their insufficient impact on their own." (PMID 40076506, 2025). "Several mechanisms of resistance of cancer cells to cyclin-dependent kinase inhibitors (CDKi) have been identified, including the upregulation of metabolic regulators such as glutaminase." (PMID 40696167, 2025). "It was known that glutaminase plays a crucial role in cancer cell metabolism by catalyzing the conversion of glutamine to glutamate, which fuels various biosynthetic pathways essential for tumor growth and survival." (PMID 40850948, 2025). "Previous research demonstrated that circRNA circ_0000003 facilitated GLS expression in tongue squamous cell carcinoma cells, indicating that circRNAs can regulate GLS expression and affect glutamine metabolism and cancer progression." (PMID 40567251, 2025). "Elevated extracellular cystine levels can enhance glutaminase activity by depleting intracellular glutamate, thereby increasing cancer cell reliance on glutaminase for glutamate replenishment." (PMID 40535116, 2025). "Cancer cells seem to require glutamine for increased biosynthetic activity, with its conversion to glutamate by glutaminase (GLS) being a critical step." (PMID 40386930, 2025). "Collectively, these findings highlight the significance of targeting glutamine metabolism in cancer therapy, with glutaminase inhibitors demonstrating substantial preclinical efficacy." (PMID 40535116, 2025). "CB-839, a glutaminase inhibitor, targets glutamine metabolism and has shown efficacy in preclinical studies across various cancers by depriving cells of a critical substrate needed for the TCA cycle and biosynthetic reactions." (PMID 40868156, 2025). "These transporters, as well as enzymes such as glutaminase (GLS) and phosphoglycerate dehydrogenase (PHGDH), contribute to the metabolic flexibility and adaptability of cancer cells, allowing them to thrive in nutrient-deficient tumor microenvironments." (PMID 39973065, 2025). "The study also found that the overexpression of Jun significantly enhanced GLS expression, and sensitised cancer cells to GLS inhibitors." (PMID 39859271, 2025).
cancer (continued). "Further studies revealed that Sirt5 plays an important role in supporting cancer cell metabolism by regulating various enzyme activities and protecting glutaminase C (GAC), an enzyme essential for glutamine catabolism, from degradation." (PMID 40598593, 2025). "It is designed to intervene in the energy metabolism of tumor cells, particularly those cancers dependent on glutamate metabolism, by inhibiting GLS." (PMID 40696413, 2025). "For instance, CB-839 is a small molecule that inhibits glutaminase, thereby blocking cancer cell's ability to utilize glutamine for biosynthesis and energy production." (PMID 39744225, 2025). "Glutaminase inhibition then suppresses cancer cell growth, elevates intracellular ROS, and concurrently upregulates uridine phosphorylase 1 (UPP1), which promotes 5-FU conversion to its active form and thereby enhances 5-FU efficacy." (PMID 41488637, 2025). "Current research primarily focuses on blocking glutamine utilization in cancer cells using GLS inhibitors such as CB-839 and JHU083." (PMID 41179661, 2025). "Glutaminase‐1 (GLS1) has garnered considerable interest as a metabolic target in cancer due to its heightened involvement and activity." (PMID 40259435, 2025). "Outside the context of chemoresistance, there are several examples of exploiting the glutaminase activity of ASNase for targeting glutamine‐dependent cancer cells, including both solid and hematological cancer‐derived models." (PMID 40784667, 2025). "The enzyme glutaminase (GLS), which catalyzes the first step of glutaminolysis by hydrolyzing glutamine to glutamate, has emerged as a critical regulator of cancer metabolism." (PMID 40278350, 2025). "Another intriguing treatment approach for cancer is to target glutamine metabolism, specifically by inhibiting glutaminase (GLS1)." (PMID 40710528, 2025). "In particular, we review the reported drugs targeting glutaminase and glutamine uptake for efficient cancer treatment." (PMID 38510646, 2024). "Recent findings have suggested that GLS is involved in acquiring radioresistance, making GLS inhibitors a promising strategy to improve the outcomes of cancer radiotherapy." (PMID 39199642, 2024). "The overexpression of glutaminase is reported to influence cancer growth and metastasis through glutaminolysis." (PMID 38939098, 2024). "CB-839, a first-in-class glutaminase inhibitor, is actively explored as metabolic intervention for the treatment of multiple types of cancer, but its clinical benefit is limited as monotherapy." (PMID 38830868, 2024). "Antagonism of Gln metabolism has been studied as a foundational approach for targeting cancer metabolism by blocking glutamine transporters or glutaminase." (PMID 38473414, 2024). "Current strategies targeting glutamine metabolism in cancer cells focus on its depletion, glutaminase inhibition, and inhibition of glutamine uptake by blocking its membrane transporters." (PMID 38539506, 2024). "The C-terminal truncated splice variant of the kidney-type glutaminase is named glutaminase C (GAC), and it has been directly implicated in the progression and survival of numerous aggressive cancers." (PMID 39338163, 2024). "Many studies are currently focusing on inhibiting GLS, which has been proven to have a critical role in various types of cancer." (PMID 38790264, 2024). "GLS expression in cancer cells has been reported to be upregulated either by c-Myc or c-Jun, and the JNK/c-Jun pathway is activated in some infected cells." (PMID 39662828, 2024). "Glutaminase (GLS) breaks down glutamine into glutamate and has been considered to be a possible target due to its elevated expression in cancer cells." (PMID 39329757, 2024). "The glutaminase enzymes GAC and GLS2 have both been implicated in cancer progression due to the upregulation of their expression and catalytic activities." (PMID 38438397, 2024). "Briefly, GLS expression level was down-regulated significantly in 17 human carcinomas and up-regulated in 11 other cancers." (PMID 38566121, 2024).
cancer (continued). "In this sense, mitochondrial GLS is involved in the first step of glutamine catabolism, one of the main energy sources in the context of cancer." (PMID 38542254, 2024). "On the contrary, GLS expression was increased in almost all cancer cell lines, and the highest expressed tissue was the kidney (p = 2.2e-16)." (PMID 38566121, 2024). "A pathway frequently altered in cancer is glutaminolysis, whereby glutaminase (GA) catalyzes the main step as follows: the deamidation of glutamine to form glutamate and ammonium." (PMID 38929183, 2024). "Glutaminolysis, facilitated by glutaminase, becomes a vital process for cancer cells exhibiting glutamine addiction." (PMID 38474093, 2024). "Since then, other enzymes like arginine deiminase, arginase, glutaminase, methionase, lysine oxidase, and phenylalanine ammonia lyase are being explored for cancer treatment." (PMID 38454103, 2024). "Compounds designed to inhibit specific metabolic pathways, such as glutaminase inhibitors and mTOR inhibitors, are showing promise in clinical settings, addressing the metabolic vulnerabilities of cancer cells." (PMID 39456607, 2024). "Of note, the FDA-approved CsA, as a chemical inducer of NRF2 degradation, exhibits a significantly synergistic anti-cancer effect when administered as a combination therapy alongside the clinical glutaminase inhibitor CB-839 in NRF2-hyperactivated NSCLC." (PMID 38830868, 2024). "Targeting GLS can disrupt glutamine metabolism, which is essential for the rapid proliferation of cancer cells." (PMID 39534557, 2024). "Among the more recent strategies targeting glutamine metabolism for cancer therapy is the inhibition of glutaminase." (PMID 38473414, 2024). "This ‘glutamine addiction’ of cancer cells is supported by an overexpression of the mitochondrial enzyme glutaminase, which catalyzes the first step of glutaminolysis." (PMID 39338163, 2024). "This upregulation of glutaminase enables cancer cells to utilize glutamine as a fuel source and support their enhanced metabolism and growth." (PMID 39170262, 2024). "Heat shock factor 1 (HSF1) can inhibit the interaction of miR-137 and GLS to promote glutamine catabolism and activate mTOR signaling, which contributes to cancer development." (PMID 38238756, 2024). "Inhibiting glutamine metabolism, specifically via glutaminase inhibition, has been explored as a therapeutic strategy to induce reactive oxygen species (ROS) overproduction, potentially leading to cancer cell devastation." (PMID 38474093, 2024). "Recent studies have further established that EZH2 plays a pivotal role in regulating cancer cell metabolism, particularly glutamine metabolism, by inhibiting GLS activity." (PMID 39518098, 2024). "Because the glutaminase enzymes are often highly expressed and activated in cancer and viral-infected host cells, as compared to normal healthy cells, small molecule inhibitors targeting these enzymes offer a potentially safe therapeutic strategy." (PMID 39662828, 2024). "Beyond glutaminase inhibition and modulation of transport systems, other targeted therapeutic approaches are being explored to disrupt glutamine metabolism in cancer cells." (PMID 38473414, 2024). "The catabolism of glutamine initiates with its conversion to glutamate, which can be catalyzed by glutaminase (GLS) in many cancer cells, a process that also releases a free amide nitrogen molecule to biosynthetic pathways." (PMID 38539506, 2024). "Glutaminase is also essential to cancer cell aggressiveness, including cell migration and invasion processes." (PMID 38965208, 2024). "The critical role of GLS as a key enzyme involved in glutamine metabolism has emerged as a promising approach for cancer therapy." (PMID 38459595, 2024). "In 2014, the GLS inhibitor CB-839, undergoing clinical trials, was reported to possess potent anti-tumor activity, offering a novel avenue for targeted cancer therapy through modulation of glutamine metabolism." (PMID 38459595, 2024).